LOXL2 (lysyl oxidase like 2)
Diseases named in the same sentence as LOXL2 in open-access papers (continued):
Sharing a sentence is not in itself a finding about the gene and the disease.
asthma (2 papers, 2022 to 2024). "Our data suggest heterogeneity in LOXL2 expression between donors, which may be reflective of disease severity; however, the current study was not sufficiently powered to detect associations between LOXL2 expression and asthma severity." (PMID 34996828, 2022). "In our study, the KEGG pathway enrichment analysis of RNA-sequencing indicated that LOXL2 knockdown in OVA-induced asthma models significantly affected the PI3K-AKT signaling pathway, which contains the most down-regulated DEGs." (PMID 38824593, 2024). "Based on the results of bioinformatics analysis, IHC staining was performed on bronchial epithelial biopsy specimens of asthma patients and healthy controls, and then demonstrated LOXL2 was highly expressed in airway epithelium of asthmatics." (PMID 38824593, 2024). "Correspondingly, we analyzed the transcriptome changes of airway epithelial cells under pathological conditions in vitro and in vivo, and observed that LOXL2 gene was significantly upregulated in the airway epithelium cells of asthma." (PMID 38824593, 2024). "Given that LOXL2 can be released extracellular, we detected serum LOXL2 level and found that it was significantly elevated in patients with asthma." (PMID 38824593, 2024). "Taken together, we demonstrated that LOXL2 is increased in the airway epithelium of asthma, and regulates EMT and ECM deposition partly via the AKT signaling pathway." (PMID 38824593, 2024). "The IF staining of lung tissue sections also showed that LOXL2 was elevated in airway epithelium of OVA-induced asthma models." (PMID 38824593, 2024). "We show that LOXL2 expression is increased in asthma, and that LOXL2 inhibition reduces ASM cell ECM stiffness and TGF-β activation in vitro and reduces airway remodelling in an in vivo asthma model." (PMID 34996828, 2022). "A chronic ovalbumin (OVA) model of asthma was used to study the effect of LOXL2 inhibition on airway remodelling." (PMID 34996828, 2022). "Our data confirm an earlier study showing increased LOXL2 gene expression in asthma, but also demonstrate that LOXL2 protein is increased in asthmatic ASM." (PMID 34996828, 2022). "Additionally, in light of bidirectional interaction between inflammation and remodeling of airway epithelium in asthma, future studies should also explorer the effects and mechanisms of LOXL2 on airway inflammation." (PMID 38824593, 2024). "Combined with the findings in biopsies from asthma patients, we speculate that airway epithelial cells may be an important source of serum LOXL2." (PMID 38824593, 2024). "Finally, several novel functions of LOXL2, such as regulating transcription and epigenetic inheritance, have recently been identified, which is worthy of further investigation in asthma." (PMID 38824593, 2024). "The mechanisms driving enhanced LOXL2 expression in asthma are likely to be complex and multifactorial, and may potentially include transcriptional regulation, microRNAs, alternative splicing and/or epigenetic regulation." (PMID 34996828, 2022). "Taken together, our findings suggest that inhibition of LOXL2 may have merit as an approach to reduce airway remodelling in severe asthma." (PMID 34996828, 2022). "This raises the possibility that increased LOXL2 expression in asthma might impact a large number of pathways relevant to asthma pathogenesis that are independent of its matrix cross-linking enzymatic activity." (PMID 34996828, 2022). "We demonstrate for the first time that LOXL2 expression is increased in asthma and we have shown that LOXL2 inhibition in vivo may reduce airway remodelling." (PMID 34996828, 2022). "LOXL2 is increased in several diseases associated with tissue remodelling, but the functional consequences of increased LOXL2 in asthma have never been studied." (PMID 34996828, 2022). "Thus, further exploration of the relationship and potential mechanisms between LOXL2 and asthma may provide meaningful insights for developing promising treatments." (PMID 38824593, 2024).
asthma (continued). "In this article, we noticed that LOXL2 is highly expressed in asthmatics (serum and airway epithelium) and OVA-induced asthma models (airway epithelium and lung tissues)." (PMID 38824593, 2024). "Taken together, the results demonstrated that epithelial LOXL2 plays a role in asthmatic airway remodeling partly via the AKT signaling pathway and highlighted the potential of LOXL2 as a therapeutic target for airway remodeling in asthma." (PMID 38824593, 2024). "Crucially, we show that LOXL2 inhibition reduces ECM stiffness and TGF-β activation in vitro, and can reduce subepithelial collagen deposition and ASM thickness, two features of airway remodelling, in an OVA mouse model of asthma." (PMID 34996828, 2022). "To date, there have been no studies investigating a role for LOXL2 in asthma pathogenesis or airway remodelling." (PMID 34996828, 2022). "To further investigate whether LOXL2 expression is increased in asthma we stained parallel sections of airway biopsies from nonasthmatic and asthmatic donors for both α-SMA and LOXL2." (PMID 34996828, 2022).
atherosclerosis (2 papers, 2023 to 2025). A disease characterized by the build-up of fatty material and calcium deposition in the arterial wall resulting in partial or complete occlusion of the arterial lumen. "Therapeutic interventions targeting LOX, such as β-aminopropionitrile (BAPN) and LOXL2-specific inhibitors like GSK2878163, have demonstrated efficacy in mitigating ECM cross-linking and decelerating atherosclerosis progression in animal models." (PMID 40661776, 2025). "In the training dataset GSE97210, SLC31A1, ATP7A, SLC31A2, UBE2D1, CP and FDX1 were highly expressed while LOXL2, COA6 and SOD1 were lowly expressed in the atherosclerosis group as showed in the bar charts." (PMID 37324184, 2023).
breast cancer disease (2 papers, 2016). "In human breast disease, collagen crosslinking by lysyl oxidase enzymes such as lysyl oxidase-like 2 (LOXL2) promotes cancer risk as well as progression." (PMID 27142210, 2016). "This may pave the way for new therapeutic strategies targeting cellular LOXL2 in addition to extracellular LOXL2, as means to prevent and treat metastatic recurrence of breast cancer disease." (PMID 27655685, 2016).
breast invasive ductal carcinoma (2 papers, 2021 to 2022). "Our results suggest that OSM-induced LOXL2 protein expression may be correlated to the development of more aggressive invasive ductal carcinomas due to the incremental increase in LOXL2 with OSM exposure." (PMID 34011405, 2021).
cardiac hypertrophy (2 papers, 2021 to 2022). "The association of LOXL2 with cardiac hypertrophy is also confirmed in several cardiovascular diseases with cardiac hypertrophy." (PMID 36159334, 2022). "Ang II significantly increased mRNA and protein expressions of LOXL2 and increased mRNA levels of myocardial hypertrophy markers, including ANP, BNP, and β-MHC in H9c2 cells." (PMID 36159334, 2022). "Ang II increases mRNA and protein expressions of LOXL2 and promotes cardiac hypertrophy and inflammatory cytokine production." (PMID 36159334, 2022). "Small interfering RNA (siRNA) mediated LOXL2 gene silencing was used to evaluate cardiac hypertrophy and related markers." (PMID 36159334, 2022). "Immunofluorescence was carried out in H9c2 cells with an antibody of α-actinin to explore the function of LOXL2 silencing in cardiac hypertrophy." (PMID 36159334, 2022). "LOXL2 silencing by siRNA markedly suppressed cardiac hypertrophy and proinflammatory cytokine production." (PMID 36159334, 2022). "Our findings showed that LOXL2 silencing has protective effects by inhibiting cardiac hypertrophy and inflammation in cardiomyocytes induced by Ang II." (PMID 36159334, 2022). "Meanwhile, LOXL2 silencing protects against Ang II-induced cardiac hypertrophy via inhibition of the EMT process and down-regulation of the TGF-β1/Smad3/NF-κB pathway." (PMID 36159334, 2022). "Therefore, LOXL2 expression is increased in diseases with cardiac hypertrophy, such as cardiac tissue of hypertensive rats with left ventricular hypertrophy and lung tissue of hypoxia-exposed pulmonary hypertension mice." (PMID 36159334, 2022). "LOXL2 catalyzes crosslinking of collagens and elastin and is a contributor to cardiac hypertrophy." (PMID 36159334, 2022). "This is the first report about the modulation of LOXL2 on EMT in cardiac hypertrophy." (PMID 36159334, 2022). "The expression of LOXL2 and myocardial hypertrophy marker will be evaluated." (PMID 36159334, 2022). "The results indicate LOXL2 might involve the process of cardiac hypertrophy." (PMID 36159334, 2022). "However, the detailed mechanism of LOXL2 in cardiac hypertrophy remains unclear." (PMID 36159334, 2022). "As overexpression of LOXL2 alone is insufficient to induce EndMT in endothelial cells, the possibility cannot be ruled out that TGF-β1 enhances LOXL2 expression making a positive feedback loop in cardiac hypertrophy." (PMID 36159334, 2022). "Our data speculated that LOXL2 might be a potential contributing factor to Ang II-induced cardiac hypertrophy, and TGF-β1/Smad3/NF-κB is involved in a signal axis and might be a potential strategy in treating cardiac hypertrophy." (PMID 36159334, 2022).
colorectal adenocarcinoma (2 papers, 2021 to 2022). The most common type of colorectal carcinoma. "Among the genes associated with mbesQTLs and known to be differently expressed in colorectal adenocarcinoma tissue according to The Cancer Genome Atlas database, USP14, LOXL2 (lysyl oxidase-like 2) and TP63 (tumor protein 63) link the microbiota composition with cancer development." (PMID 35794137, 2022).
diabetic nephropathy (2 papers, 2018 to 2025). "This establishes a critical pathogenic role for endothelial-derived LOX and LOXL2 in promoting mesangial cell injury, oxidative stress, and fibrosis, key features of diabetic nephropathy." (PMID 41355449, 2025). "This work establishes endothelial LOX and LOXL2 as lynchpins within the dysregulated signaling network governing glomerular injury in diabetic nephropathy." (PMID 41355449, 2025). "Consistent with the RNA-seq data, quantitative real-time PCR (qPCR) analysis confirmed a substantial elevation in renal mRNA levels of Lox, Loxl1 and Loxl2 in the diabetic nephropathy model group relative to normal controls." (PMID 41355449, 2025). "Taken together the findings obtained from this study indicate an upregulation of LOXL2 in a mouse model of diabetic nephropathy and beneficial effect of LOXL2 inhibition on the structure and barrier function of the glomerulus." (PMID 29930330, 2018). "Using the novel, selective, small molecule LOXL2-inhibitor PXS-S2B in a mouse model of diabetic nephropathy we demonstrated both a structural and functional benefit." (PMID 29930330, 2018). "We firstly, and to date, uniquely demonstrated increased levels of LOXL2 in renal cortices of mice with diabetic nephropathy." (PMID 29930330, 2018). "Thus, LOXL2 may be a potential therapeutic target in diabetic nephropathy." (PMID 29930330, 2018). "Thus, targeting LOXL2 may prove to be a useful strategy to prevent diabetic nephropathy." (PMID 29930330, 2018).
idiopathic dilated cardiomyopathy (2 papers, 2016 to 2019). Decreased function of the heart associated with cardiac enlargement and congestive heart failure, of unknown cause. "Similarly, the expression of LOXL2 is increased in patients with ischemic or idiopathic dilated cardiomyopathy in which cardiac LOXL2 correlates with collagen cross-linking and with the impairment of diastolic function." (PMID 31615160, 2019). "Quantification of messenger RNA (mRNA) revealed that LOXL2 expression correlated well with the expression of fibrillar collagen genes (COL1A and COL3A) in ventricular tissues of healthy donor hearts (n=8) and of hearts from patients with idiopathic dilated cardiomyopathy (IDCM, n=10)." (PMID 27966531, 2016).
IgA nephropathy (2 papers, 2012 to 2018). "A comparable increase in LOXL2 expression was also seen by real-time PCR in micro-dissected tubulointerstitium from patients with IgA nephropathy and hypertensive nephrosclerosis, suggesting a general association between LOXL2 expression and the presence of CKD." (PMID 23259746, 2012).
invasive breast carcinoma (2 papers, 2004 to 2022). A carcinoma that infiltrates the breast parenchyma. "LOXL2 protein has been previously reported to be expressed in normal mammary ducts and increased in invasive breast carcinoma cells." (PMID 14737219, 2004).
keratoconus (2 papers, 2019 to 2023). A degenerative, structural disorder of the eye, characterized by a cone-shaped protrusion of the cornea. "Although LOXL2 has previously been linked to keratoconus and may enhance the development of the disease, the clinical and genetic associations seem to suggest that it is especially the PIKFYVE gene that contributes to the development of the disease." (PMID 37895187, 2023). "In keratoconus, a disease characterized by irregular astigmatism resulting in significant visual impairment, LOXL3 expression is downregulated, as well as LOXL2 and LOXL4 expression, suggesting that LOX members may be involved in keratoconus pathogenesis." (PMID 31340433, 2019).
metastatic melanoma (2 papers, 2018 to 2020). A melanoma that has spread from its primary site to another anatomic site. "LOXL3 expression is thus associated with both primary and metastatic melanomas, and considerably upregulated compared to other LOX family members frequently associated with cancer, such as LOX and LOXL2." (PMID 29229995, 2018).
neuroblastoma (2 papers, 2015 to 2022). Neuroblastoma (NB) is the most common solid, extracranial childhood tumor. "KDM3A has also been implicated in neuroblastoma metastasis and the HDM enzyme KDM4C has been shown to be a regulator of BCa lung metastasis and an activator of LOXL2 expression." (PMID 25488809, 2015). "Moreover, the neuroblastoma mesenchymal transcriptional signature, repressed after BAF disruption, is determined by a specific super-enhancer configuration, and many of these genes (LOXL2, SNAI2, CDH11, ITGAV) are associated with chromatin repressive events." (PMID 36057593, 2022). "Neuroblastoma-specific mesenchymal transcriptional signature was also repressed after BAF disruption in neuroblastoma cells, involving the epigenetic repression of key regulators of the mesenchymal phenotype, such as SNAI2, CDH11, CDH2, LOXL2 and NOTCH2." (PMID 36057593, 2022).
nonalcoholic fatty liver disease (2 papers, 2024). "Nonetheless, according to Dongiovanni and colleagues, LOXL2 (cg04028450) is associated with T2DM, and its upregulation has been observed in nonalcoholic fatty liver disease patients with T2DM." (PMID 39415250, 2024).
oesophageal cancer (2 papers, 2023). "The recently described constitutive L2ΔE13-KI splice variant model has been crucial in identifying the novel deacetylase activity of Loxl2 and the L2ΔE13 variant, which promotes metabolic reprogramming and tumour progression in oesophageal cancer." (PMID 37762708, 2023). "The endogenous expression level of LCN2 and LOXL2 was examined in eight oesophageal cancer cell lines, with human 293T as a control." (PMID 37753805, 2023). "Our results showed that an LCN2/LOXL2/MMP9 ternary complex was formed in oesophageal cancer, with a distinctive intracellular and extracellular interaction pattern." (PMID 37753805, 2023). "This suggested that the ternary complex of LCN2/LOXL2/MMP9 existed in oesophageal cancer cells." (PMID 37753805, 2023). "Notably, this study also reported that overexpression of the LOXL2/L2ΔE13 variant and decreased acetylation of aldolase A at K13 residue (one of the deacetylating targets of LOXL2) served as predictors of poor clinical behaviour in oesophageal cancer patients." (PMID 37762708, 2023). "Therefore, the LCN2/LOXL2/MMP9 ternary complex can promote the invasion of oesophageal cancer cells by elevating the expression of MMPs to degrade gelatin and fibronectin." (PMID 37753805, 2023). "Based on LCN2/LOXL2, LCN2/MMP9 and LOXL2/MMP9 protein–protein interactions, we further elucidated the molecular and cellular mechanisms underlying the LCN2/LOXL2/MMP9 ternary complex that promoted migration and invasion of oesophageal cancer cells, playing a synergistic role." (PMID 37753805, 2023). "LCN2, LOXL2, and MMP9 formed a ternary complex in oesophageal cancer cells, but the biological function of the ternary complex remained to be explored." (PMID 37753805, 2023). "The SRCR structure is a key domain through which LOXL2 interacts with both LCN2 and MMP9 to play an important biological role in oesophageal cancer." (PMID 37753805, 2023). "The LCN2/LOXL2/MMP9 complex remodels the ECM and activates the FAK/AKT/GSK3β signalling pathway to enhance SPOCK1 expression, promoting the migration and invasion of oesophageal cancer cells." (PMID 37753805, 2023). "Considering the crosstalk of functional roles of LCN2, MMP9 and LOXL2 in tumour progression, we hypothesized that an LCN2/LOXL2/MMP9 ternary complex might exist in oesophageal cancer and play a synergistic role in biological function." (PMID 37753805, 2023). "Therefore, LCN2/LOXL2/MMP9 activated the FAK/AKT/GSK3β signalling pathway to enhance SPOCK1 expression and remodel the ECM, thus promoting the migration and invasion of oesophageal cancer cells." (PMID 37753805, 2023). "Moreover, both Transwell assays and invasion assays showed that overexpression of LCN2/LOXL2, LCN2/MMP9 and LOXL2/MMP9 enhanced the migration and invasion of oesophageal cancer cells." (PMID 37753805, 2023).
pancreas carcinoma (2 papers, 2016 to 2025). "We generated stable pancreatic carcinoma cells in which LOXL2 was silenced by siLOXL2, (MIA PaCa-2 and PANC-1) or ectopically expressed by pc3.1- LOXL2 (AsPC-1 and BxPC-3)." (PMID 27285767, 2016).
pancreatic adenocarcinoma (2 papers, 2020 to 2023). "In pancreatic ductal adenocarcinoma LOXL2 stabilises HIF1 by inhibiting HIF1 hydroxylation and enhancing the expression of HIF1, increasing the transcription of multiple glycolytic genes, thereby promoting aerobic glycolysis (Warburg effect) and pancreatic adenocarcinoma progression." (PMID 37762708, 2023). "However, then, simtuzumab, a function-blocking antibody against LOXL2 with an antidesmoplastic effect in vitro, did not improve the clinical results in patients with KRAS-mutated colorectal or pancreatic adenocarcinoma." (PMID 33379400, 2020).
steatosis (2 papers, 2019 to 2022). Increased lipid within the cytoplasm of cells. "Again, patients with higher expression of LOXL2 had steatosis and ballooning in the liver biopsy." (PMID 31426495, 2019).
thyroid cancer (2 papers, 2021 to 2022). "GINS2 promotes cell proliferation and inhibits cell apoptosis by regulating CITED2 and LOXL2 in thyroid cancer." (PMID 34288816, 2021). "For example, a previous study found that inhibiting GINS2 expression promotes apoptosis of thyroid cancer cells by mediating the down-regulation of downstream proteins CITED2 and LOXL2." (PMID 36092720, 2022).
uterine cancer (2 papers, 2023 to 2024). Primary or metastatic malignant neoplasm involving the uterine corpus and/or the cervix. "Interestingly, low LOXL2 and high H3K36ac levels were associated with poor prognosis in uterine endometrial patients, suggesting nuclear LOXL2 as a protective factor against uterine cancer development." (PMID 37762708, 2023).
adolescent idiopathic scoliosis (1 paper, 2011). A scoliosis with no known cause arising in adolescent. "We hypothesized that common polymorphisms in the five human lysyl oxidase genes (LOX, LOXL1, LOXL2, LOXL3, and LOXL4) may be associated with the phenotype of adolescent idiopathic scoliosis." (PMID 21740577, 2011).
airway hyperresponsiveness (1 paper, 2024). "The assessment of airway resistance showed that there were marked airway hyperresponsiveness in OVA-treated mice, which could be partially alleviated in the condition of LOXL2 knockdown." (PMID 38824593, 2024).